MIR151B (microRNA 151b)
Synonyms: hsa-mir-151b
Gene: MicroRNA gene on chromosome 14 (100,109,419 to 100,109,514, reverse strand). Ensembl gene ENSG00000265154.
Homologues: Orthologues: chimpanzee MIR151B (99% identical). Paralogues in human: MIR151A (29% identical), MIR28 (28% identical).